TFCP2 (transcription factor CP2)
Diseases named in the same sentence as TFCP2 in open-access papers (continued):
Sharing a sentence is not in itself a finding about the gene and the disease.
sarcoma (continued). "Taken together, TFCP2-rearranged sarcoma likely represents a separate entity characterized by distinct transcriptional and DNA methylation profiles, an unusual degree of genomic instability, truncated ALK variants, ALK and TERT overexpression, and recurrent CDKN2A/MTAP co-deletions." (PMID 38168093, 2024). "Furthermore, PTH1R, encoding the parathyroid 1 receptor, was also highly expressed in FUS/EWSR1-TFCP2 sarcomas and strongly induced by TFCP2 fusions in immortalized cells." (PMID 38168093, 2024). "Specifically, TFCP2-rearranged sarcoma expressed a TERT variant lacking exons 1 and 2 (Δex1-2), and intronic RNAs were transcribed in the reverse direction, starting exactly at the TFCP2 binding region." (PMID 38168093, 2024). "Therefore, PRMT5 inhibitors and antifolate drugs may be potential therapeutic options to pursue in TFCP2 fusion sarcomas with MTAP deletion." (PMID 40361368, 2025). "On NGS sarcoma panel from MedGenome, EWSR1-TFCP2 fusion oncogenic was detected, suggestive of RMS with TFCP2 mutation, suggesting that he was initially misdiagnosed." (PMID 41497928, 2025). "Finally, our findings suggest that patients with TFCP2-rearranged sarcomas, which are refractory to conventional chemotherapy, may benefit from combination treatments that include platinum derivatives, ALK inhibitors, and, in the case of CDKN2A/MTAP co-deletions, drugs targeting PRMT5." (PMID 38168093, 2024). "RNA-seq has since allowed the characterization of novel fusion genes such as CIC-NUTM1, TFCP2-rearranged, EWSR1-SSX1, as well as the identification of NTRK-rearranged sarcomas or NRG1-fused sarcomas." (PMID 35626152, 2022). "YAP has been reported to be expressed in 50% of sarcomas and YAP interaction with TFCP2 controls PDE3A expression." (PMID 30956759, 2019). "Despite the prevalence of ALK alterations and overexpression, most TFCP2 fusion sarcoma patients treated with ALK inhibitors have not responded well." (PMID 40361368, 2025). "Unlike other fusion-driven sarcomas, TFCP2-rearranged tumors exhibit genomic instability and signs of defective homologous recombination." (PMID 38168093, 2024). "Collectively, our data show that TFCP2-rearranged neoplasms represent an unusual disease whose molecular landscape suggests categorization as undifferentiated sarcoma rather than RMS." (PMID 38168093, 2024). "Interestingly, the fusion partner of TFCP2 in this entity is one of the FET proteins (i.e., FUS or EWSR1) a transcription factor and fusion partner well known from Ewing sarcoma and other sarcoma entities." (PMID 36551545, 2022).
liver cancer (10 papers, 2019 to 2024). An epithelial or non-epithelial malignant neoplasm that arises from the liver. "In liver cancer, CCT3 was elevated and co-interacted with the transcriptional co-activator YAP, which is negatively regulated by the Hippo pathway, and transcription factor CP2 (TFCP2), a Hippo-independent oncoprotein in liver cancer." (PMID 35602608, 2022). "YAP and TFCP2 are recognized as upstream triggers to increase the protein stability of YAP and TFCP2 in liver cancer cells." (PMID 36185198, 2022). "Regulation of TFCP2 expression in liver cancer and expression of treatment-resistant and senescence-related gene have already been reported." (PMID 34804919, 2021). "CCT3 functioned as a trigger of YAP and TFCP2 to affect tumorigenesis and served as a potential biomarker in liver cancer." (PMID 33815471, 2021). "Tissue microarray analysis revealed a statistically significant positive correlation between YAP and TFCP2 in liver cancer samples, consistent with the notion that TFCP2 cooperates with Yap to stimulate liver malignancy." (PMID 33869224, 2021). "Together, CCT3 acts as a trigger of YAP and TFCP2 to affect tumourigenesis and serves as a potential therapeutic target and biomarker in liver cancer." (PMID 31501420, 2019). "Taken together, in this paper, CCT3 has been identified as an upstream trigger to increase the protein stability of YAP and TFCP2 in liver cancer cells." (PMID 31501420, 2019). "Here, we uncovered another tumour suppressive role of PCBP2 to reduce the protein stability of YAP and TFCP2 in liver cancer." (PMID 31501420, 2019). "Additionally, CCT3 can also function independently by interacting with YAP and TFCP2 in liver cancer, thereby preventing the PCBP2-induced ubiquitination of these proteins." (PMID 39210442, 2024). "Recently, we reported that the protumourigenic roles of YAP in liver cancer are indispensable for transcription factor CP2 (TFCP2) in a Hippo-independent manner; however, proteins that act upstream to simultaneously control YAP and TFCP2 remain unclear." (PMID 31501420, 2019). "For tumor cells, transcription factor CP2 (TFCP2) expression can control the occurrence and regulate the development of tumor cells such as liver cancer." (PMID 35193647, 2022). "Here, we tested whether the relationship among CCT3, YAP, TFCP2 and PCBP2 is functional in maintaining transformative phenotypes in liver cancer cells." (PMID 31501420, 2019). "Spearman’s rank correlation coefficient analysis was then performed according to the IRS to analyse the data from 167 tumour specimens, and significant correlations among YAP, CCT3 and TFCP2 were revealed, suggesting that the CCT3-YAP-TFCP2 loop might be important in liver cancer." (PMID 31501420, 2019).
pancreatic cancer (9 papers, 2017 to 2025). "In conclusion, our study reveals a new mechanism underlying the TFCP2 regulation of pancreatic cancer cell senescence, providing a new target for the treatment of pancreatic cancer." (PMID 34804919, 2021). "In conclusion, our study reveals the regulation of pancreatic cancer cell senescence and the underlying mechanism, and suggests that TFCP2 is a potential target for treating pancreatic cancer." (PMID 34804919, 2021). "In order to further reveal the mechanism underlying the inhibition of pancreatic cancer cell senescence by TFCP2, proteins interacted with TFCP2 were analyzed by mass spectrometry (MS)." (PMID 34804919, 2021). "In this study, we investigated the effect of TFCP2 expression on the senescence of pancreatic cancer, and explored the underlying molecular mechanism." (PMID 34804919, 2021). "We found that the expression level of TFCP2 was higher in pancreatic cancer tissues with Kras mutation." (PMID 34804919, 2021). "In this study, we found upregulation of TFCP2 expression in pancreatic cancer was associated with KRAS mutation." (PMID 34804919, 2021). "Furthermore, SREBP2 interacts with transcription factor CP2 (TFCP2) in pancreatic cancer cells, allowing them to overcome KRAS mutation-induced senescence." (PMID 40308757, 2025). "Moreover, the expression level of TFCP2 was higher in pancreatic cancer cells with KRAS mutation." (PMID 34804919, 2021). "This offers a new strategy for the treatment of pancreatic cancer by suppression of up-stream TFCP2 signaling and induction of senescence." (PMID 36768320, 2023). "Searching the GEPIA database showed that the mRNA expression levels of TFCP2 were positively correlated with those of the SMAD2 in pancreatic cancer cells." (PMID 35193647, 2022). "The ITGA2 inhibited the SMAD2 expression by interacting with TFCP2 and inhibiting its nuclear translocation in the pancreatic cancer cells." (PMID 35193647, 2022). "Taken together, these findings indicated that TFCP2 induced the SMAD2 expression by acting as a transcription factor in the pancreatic cancer cells." (PMID 35193647, 2022). "In this study, we found that TFCP2 inhibited the senescence of pancreatic cancer cell, further enriching the functions of TFCP2 in pancreatic cancer." (PMID 34804919, 2021). "In order to further understand the function of TFCP2 in pancreatic cancer, we overexpressed TFCP2 in pancreatic cancer cell lines." (PMID 34804919, 2021). "In our previous studies, we found that TFCP2 promoted the growth, colony formation, invasion and metastasis of pancreatic cancer cells." (PMID 34804919, 2021). "In order to further analyze the expression pattern of TFCP2 in pancreatic cancer, we used immunohistochemistry to determine the expression pattern of TFCP2 in pancreatic cancer." (PMID 34804919, 2021). "In our study, we investigated the effects of TFCP2 on the synthesis of cholesterol and the senescence of pancreatic cancer cell." (PMID 34804919, 2021). "Overexpression of TFCP2 promoted the formation of spheres, and inhibited β-Gal staining, suggesting that overexpression of TFCP2 possibly promoted the stemness and inhibited the senescence of pancreatic cancer cell." (PMID 34804919, 2021). "In the previous studies, we found that high expression of TFCP2 in pancreatic cancer promoted pancreatic cancer cell growth and colony formation and activated the β-catenin/TCF signaling pathway." (PMID 34804919, 2021). "We found that overexpression of constitutively active Kras in normal pancreatic cancer cells promoted the expression of TFCP2." (PMID 34804919, 2021). "One of the most interesting findings of our study is that TFCP2 inhibits the senescence of pancreatic cancer cell." (PMID 34804919, 2021). "In this study, TFCP2 (transcriptional factor CP2) expression in pancreatic cancer was detected by qPCR, immunohistochemistry and western blot." (PMID 29050300, 2017).
pancreatic cancer (continued). "Next, we examined the protein level of TFCP2 in pancreatic cancer by immunohistochemistry (IHC) and western blot." (PMID 29050300, 2017). "Western blot, colony formation assay, migration and invasion experiment were performed to investigate the effects of TFCP2 on the growth and migration of pancreatic cancer cells." (PMID 29050300, 2017). "Collectively, these data suggested that knocking down the expression of TFCP2 inhibited the metastasis of pancreatic cancer cells in vivo." (PMID 29050300, 2017). "In summary, these findings suggested that TFCP2 promoted the growth, migration and invasion of pancreatic cancer cells by activating beta-catenin/TCF signaling." (PMID 29050300, 2017). "To study the roles of TFCP2 in the progression of pancreatic cancer, we first over-expressed TFCP2 in HPAC and CFPAC cells, and examined the effects of over-expressing of TFCP2 on the growth, migration and invasion of pancreatic cancer cells." (PMID 29050300, 2017). "To understand the molecular mechanism through which TFCP2 positively regulated the growth, migration and invasion of pancreatic cancer cells, we screened the pathways regulated by TFCP2 using the reporter assay." (PMID 29050300, 2017). "The molecular mechanism investigations demonstrated the activation of beta-catenin/TCF signaling by TFCP2 in the pancreatic cancer cells." (PMID 29050300, 2017). "Further study using the TFCP2 knock out mouse model would provide novel insight into the functions of TFCP2 in pancreatic cancer." (PMID 29050300, 2017). "In this study, we have demonstrated that TFCP2, a transcription factor, was elevated in the pancreatic cancer." (PMID 29050300, 2017). "In this study, we examined the expression of TFCP2 in the pancreatic cancer, investigated its functions and explored the molecular mechanisms." (PMID 29050300, 2017). "In the functional study, we have shown that TFCP2 promoted the transformation of normal pancreatic cells, promoted the growth, migration, invasion and metastasis of pancreatic cancer cells." (PMID 29050300, 2017). "To study the expression pattern of TFCP2 in pancreatic cancer, we first examined the mRNA level of TFCP2 in 54 pancreatic cancer samples and paired adjacent normal tissues using q-PCR." (PMID 29050300, 2017). "Collectively, these results suggested that TFCP2 promoted the growth, migration and invasion of pancreatic cancer cells." (PMID 29050300, 2017). "The LC-MS/MS analysis showed that the TFCP2 could interact with ITGA2; this interaction was identified by detecting the peptides of TFCP2, which had been verified using immunoprecipitation assays in the pancreatic cancer cells." (PMID 35193647, 2022). "The RT-PCR and Western blot analyses showed that the TFCP2 silencing could significantly inhibit the transcription of the SMAD2 gene in the pancreatic cancer cells." (PMID 35193647, 2022). "In addition, the RT-PCR and Western blot analyses also revealed that the TFCP2 overexpression significantly promoted the transcription of the SMAD2 gene in pancreatic cancer cells." (PMID 35193647, 2022). "Taken together, these results indicated that the ITGA2 could inhibit the SMAD2 expression by interacting with TFCP2 in the pancreatic cancer cells." (PMID 35193647, 2022). "The present study previously found that the ITGA2 could inhibit the SMAD2 expression by interacting with TFCP2 in the pancreatic cancer cells." (PMID 35193647, 2022). "However, searching the GEPIA database showed that the mRNA expression levels of TFCP2 positively correlated with the mRNA expression levels of ITGA2 in the pancreatic cancer cells." (PMID 35193647, 2022). "Interference with the expression of TFCP2 inhibited sphere formation and increased β-Gal staining signals, suggesting that knockdown of TFCP2 could promote the senescence of pancreatic cancer cell." (PMID 34804919, 2021).
pancreatic cancer (continued). "The results suggest that inhibiting the function of TFCP2 and promoting the senescence of pancreatic cancer cell may be a new strategy for treating pancreatic cancer." (PMID 34804919, 2021). "The results showed that the expression level of TFCP2 was upregulated in pancreatic cancer." (PMID 34804919, 2021). "Next, we interfered with the expression of TFCP2 in pancreatic cancer cells." (PMID 34804919, 2021). "We have shown that the transcription factor TFCP2 was up-regulated in the pancreatic cancer." (PMID 29050300, 2017). "This study indicated that it might be promising to target TFCP2 for the treatment of pancreatic cancer." (PMID 29050300, 2017). "Moreover, down-regulation of TFCP2 impaired the migration and invasion of the pancreatic cancer cells." (PMID 29050300, 2017). "In addition, we assessed the protein level of TFCP2 in a panel of pancreatic cancer cell lines (HPAC, CFPAC, SW1990 and MiaPaca-2) and normal pancreatic cells (HPDE6C7)." (PMID 29050300, 2017). "Futhermore, we examined whether TFCP2 promoted the growth, migration and invasion of pancreatic cancer cells by activating beta-catenin/TCF signaling." (PMID 29050300, 2017). "An interesting finding of this study is the up-regulation of TFCP2 in the pancreatic cancer." (PMID 29050300, 2017). "Next, we examined the effects of TFCP2 on the motility of pancreatic cancer cells." (PMID 29050300, 2017). "Next, we knocked down the expression of TFCP2 in pancreatic cancer cells." (PMID 29050300, 2017). "In summary, our study demonstrated the oncogenic roles of TFCP2 in pancreatic cancer." (PMID 29050300, 2017). "Taken together, our study demonstrated the oncogenic roles of TFCP2 in pancreatic cancer, and suggested that TFCP2 might be a target for the treatment of pancreatic cancer." (PMID 29050300, 2017). "Over-expression of TFCP2 promoted the growth, migration, invasion and colony formation of pancreatic cancer cells, while knocking down the expression of TFCP2 inhibited the growth, migration, invasion, colony formation and metastasis of pancreatic cancer cells." (PMID 29050300, 2017). "Therefore, TFCP2 might transcriptionally induce the ITGA2 expression by acting as a transcription factor in the pancreatic cancer cells." (PMID 35193647, 2022). "Therefore, it was supposed that the ITGA2 could inhibit the SMAD2 expression via TFCP2 in the pancreatic cancer cells." (PMID 35193647, 2022). "A recent study found that transcription factor CP2 (TFCP2) interacts with SREBP2 to synergistically activate cholesterol biosynthesis and overcome cellular senescence in pancreatic cancer." (PMID 38617549, 2024). "Our previous studies showed that up-regulation of TFCP2 (transcription factor CP2) in pancreatic cancer promoted the growth and metastasis of pancreatic cancer cells." (PMID 34804919, 2021). "The interaction between exogenously expressed TFCP2 and SREBP2 was detected in pancreatic cancer cells." (PMID 34804919, 2021). "However, the functions of TFCP2 in the pancreatic cancer remain unknown." (PMID 29050300, 2017). "ITGA2 inhibited the SMAD2 expression by interacting with TFCP2 but did not change the TFCP2 expression in the pancreatic cancer cells." (PMID 35193647, 2022). "Indeed, FQI1, the inhibitor for TFCP2 exhibited antiproliferative activity in multiple cancer cell lines, suggesting the potential clinical application of FOI1 for the treatment of pancreatic cancer." (PMID 29050300, 2017). "However, whether TFCP2 plays an important role in pancreatic cancer cell senescence is not clear." (PMID 34804919, 2021).
breast carcinoma (7 papers, 2021 to 2024). "We identified and validated TMEM41B as a target of miR-660-5p in breast cancer cells, which aligns with previous findings that miR-660-5p promotes breast cancer progression by targeting TET2 and activating the PI3K/AKT/mTOR pathway and the miR-660-5p/TFCP2/CDKN1A pathway." (PMID 39709500, 2024).
cervical cancer (5 papers, 2021 to 2024). A primary or metastatic malignant neoplasm involving the cervix. "Other studies demonstrated that hsa_circ_0023404 was involved in cervical cancer by regulating miR-5047 and miR-136/TFCP2 /YAP pathway." (PMID 36352482, 2022). "hsa_circ_0023404 is also involved in cervical cancer progression through/miR-136/TFCP2/YAP axis." (PMID 36352482, 2022). "Circ_0023404 can promote cervical cancer via modulating miR‐136, TFCP2 and YAP signalling." (PMID 33942982, 2021). "The hsa_circ_0023404/miR-136/TFCP2/YAP mechanism appears to be involved in cervical cancer progression, suggesting that this signaling pathway could be a potential target for cervical cancer therapy." (PMID 33803232, 2021).
Alzheimer disease (4 papers, 2017 to 2025). A progressive, neurodegenerative disease characterized by loss of function and death of nerve cells in several areas of the brain leading to loss of cognitive function such as memory and language. "TFCP2 appears to regulate glycogen synthase kinase 3β expression that has been implicated in the pathophysiology of both mood disorders and Alzheimer’s disease (AD)." (PMID 30241344, 2018). "TFCP2 was first identified as one of the risk factor for Alzheimer disease (AD)." (PMID 29050300, 2017). "The ubiquitous expression of TFCP2 suggests its involvement in comprehensive cellular functions and diseases such as cancer, Alzheimer’s disease, and AIDS." (PMID 36741376, 2022). "Moreover, TFCP2 is a globin transcription factor that plays crucial roles in various human conditions, including cancer, Alzheimer’s disease, embryonic development, blood pressure regulation, and brain function." (PMID 40918512, 2025).
colorectal cancer (4 papers, 2018 to 2023). A primary or metastatic malignant neoplasm that affects the colon or rectum. "DNA hypermethylation promotes metastasis of colorectal cancer by regulating the binding of CEBPB and TFCP2 to CPEB1 promoters." (PMID 37771430, 2023).
spindle cell rhabdomyosarcoma (4 papers, 2023 to 2025). An uncommon variant of rhabdomyosarcoma characterized by the presence of whorls of spindle cells forming a storiform pattern. "Intraosseous spindle cell rhabdomyosarcoma is characterized by fusion genes consisting of TFCP2 or NCOA2 as one of the components, whereas their paired partners can be ESWR1, FUS (with TFCP2), and MEIS (with NOCA2)." (PMID 40563544, 2025). "In general, we find that TFCP2 fusion often results in an epithelioid and spindle cell rhabdomyosarcoma that most commonly affects young women." (PMID 40361368, 2025). "Other tumors, such as synovial sarcoma, can be distinguished from DF as it shows TLE1 positivity and SS18 rearrangement, while spindle cell rhabdomyosarcoma of the jaw shows TFCP2 rearrangement." (PMID 37602060, 2023).